EPCAM (epithelial cell adhesion molecule)
Diseases named in the same sentence as EPCAM in open-access papers (continued):
Sharing a sentence is not in itself a finding about the gene and the disease.
tumor (continued). "We found that addition of 0.5 and 1.5 μg of recombinant EpCAM reduced and abolished R&D EpCAM labeling of the SCCF-3 feline tumor cells, respectively, whereas staining was reduced but not completely inhibited on the higher-expressing MCF-7 cells." (PMID 33614766, 2021). "One obstacle is the choice of an appropriate target, as most conventional solid tumor antigens such as EpCAM, HER2 or EGFR are not tumor-specific, being expressed to various degrees in healthy tissues as well." (PMID 34484225, 2021). "EpCAM+/CD133+ LCSCs are characterized by high tumor‐initiating capacity, while EpCAM−/CD133− nonstem cells demonstrate low tumor‐initiating capacity." (PMID 33524223, 2021). "This enables ROR1 CAR expression selectively within the tumor that expresses both ROR1 and EpCAM, resulting in tumor regression without toxicity." (PMID 32185403, 2020). "Clear distribution of TEPP-DOX was observed in the tumor region, indicating that DOX intercalation had no influence on the aptamer's ability to transcytose the BBB and target EpCAM-positive cancer cells." (PMID 32027209, 2020). "The CellSearchTM, which exploits antibodies against epithelial cell adhesion molecule (EpCAM) for CTC enrichments and checks expression of cytokeratins (CKs) for CTC identification, is not the optimal tool for evaluating CTCs in every tumor type." (PMID 32098246, 2020). "Therefore, EpCAM might support cell adhesion primarily mediated by other molecules such as claudins and cadherins, and/or might preferentially play a role in adhesion of normal but not tumor cells." (PMID 32507912, 2020). "To identify the tumor cells and non-tumor lung cells, we first mapped the expression of six genes (FOLR1, AGR3, and SFTPD for normal hung lung cells, and EPCAM, MDK, and SOX4 for cancer cells) to each cluster to identify the cell types in our study." (PMID 32549766, 2020). "Transplantation of isolated EpCAM+CD45− cells from HCC patients into NOD/SCID mice initiated tumor formation, whereas EpCAM−CD45− cells failed to form tumors, suggesting that EpCAM+ confers the stem/progenitor cell trait of HCC and promotes tumor growth." (PMID 32466488, 2020). "The criteria for a cell to be identified as a CTC were as follows: nucleated (DAPI+) intact cells, positive for pan-cytokeratin 8, 18, and 19 (EpCAM+), negative for CD45, and a well-defined tumor cell-like morphology." (PMID 35582043, 2020). "To distinguish the human tumor cells, we gated out the human and mouse CD45+ cells and analyzed the non-hematopoietic cells expressing HLA-A,B,C and EpCam." (PMID 30736857, 2019). "Employing tumor-fibroblast co-culture models, we demonstrate the importance of the RGD motif for efficient transduction in 2D through the epithelial cell adhesion molecule (EpCAM), but not the epidermal growth factor receptor (EGFR)." (PMID 31811202, 2019). "We developed an epithelial cell adhesion molecule (EpCAM)-based positive method and CD45/CD66b-based negative method for isolating circulating tumor cells (CTCs) by lateral magnetophoresis." (PMID 31181790, 2019). "According to our findings, there was no concordance between the EpCAM-positive CTC-fraction and paired primary tumours in respect to the promoter methylation status of any of the genes studied, neither in early, nor in the metastatic setting." (PMID 29069768, 2017). "Clinicopathological characteristics, such as histological type, FIGO stage, tumor marker CA125, and tumor size did not significantly differ between the EpCAM-high and -low groups." (PMID 28574829, 2017). "We report for the first time, NSCLC circulating cells with tumour initiating potential and CDX generation from a patient without detectable EpCAM+/CK+ CTCs." (PMID 27013395, 2016).
tumor (continued). "Some biomarkers are over-expressed on tumor surface not on normal cells, such as HER2, EpCAM, folate receptor, epidermal growth factor receptor (EGFR) and so on, which were usually used as the tumor targets." (PMID 25819426, 2015). "The expression of tumour markers (Mucin1, EMMPRIN, EpCAM, EGFR) on TMV was low or absent, despite their presence on cells." (PMID 26626416, 2015). "By contrast, the tumor cells in the tumor described were negative for AFP, HepPar-1, K7, K19, CD34, CD56 and CD133, and positive for C-KIT and EpCAM." (PMID 25202388, 2014). "In the spike experiment using GFP non-tagged tumor cells (NCI N-87), cells with EpCAM+/CD45−/Hoechst33342+ and EpCAM−/CD45+/Hoechst33342+ were recognized as tumor cells and leukocytes, respectively." (PMID 24523941, 2014). "The cells of the tumor in the present study were positive for C-KIT, EpCAM and E-cadherin, but negative for other known HPC markers including AFP, K19, CD34, CD56, CD133 and albumin." (PMID 25202388, 2014). "EpCAM is expressed in most but not all tumors; there is downregulation with cancer progression and metastasis and cytokeratins are heterogeneously expressed in tumor cells and also may be downregulated during disease progression or in poorly differentiated tumors." (PMID 25101294, 2014). "The widely accepted concept that all positive cytokeratin and/or EpCAM and CD45 negative cells with a nucleus in cancer patients are circulating tumor cells (CTCs) has imposed a clear bias on the study of CTCs." (PMID 25101294, 2014). "The widely accepted concept that all cytokeratin and/or EpCAM positive, CD45 negative cells with a nucleus in cancer patients are circulating tumor cells (CTCs) has imposed a clear bias on the study of CTCs." (PMID 23653529, 2013). "EpCam is expressed in most but not all tumors; there is downregulation with cancer progression and metastasis; cytokeratins are heterogeneously expressed in tumor cells and also may be downregulated during disease progression or in poorly differentiated tumors." (PMID 23653529, 2013). "Without adjusting for epithelium percentage, both EpCAM and CTSL levels appeared significantly higher in tumor tissues than normal tissues with a p value less than 0.001." (PMID 24289299, 2013). "We observed that the intensity of EpCAM, but not CD133 staining was a strong predictor of tumor recurrence in patients who were transplanted after TACE treatment." (PMID 23216644, 2012). "Non-tumour and tumour cultures were analyzed for expression of CALLA (myoepithelial) and EPCAM (epithelial) markers." (PMID 21521500, 2011). "Despite the requirement for IL-6 in mediating the tumor promoting abilities of fibroblasts, we found that IL-6 alone was not sufficient for expansion of CD44+/CD24−/EpCAM+ cells in the MCF7 cell line." (PMID 21957456, 2011). "Indicative of a therapeutic window, studies in mice using a BiTE binding to murine EpCAM and murine CD3 demonstrated anti-tumor activity in the absence of damage to EpCAM-expressing normal epithelia." (PMID 20976159, 2010). "However, many known CTC surface markers (e.g., EpCAM and HER2) are epithelial in nature and have little-to-no expression in more mesenchymal cells and tumor types, like TNBC." (PMID 41543394, 2026). "In contrast, while tumor cells in FVB/N mice exhibited similar EpCAM expression during the DN stage, the few surviving cells at MRD following TAC(2x,q21) treatment were negative for EpCAM." (PMID 40738896, 2025). "However, comparative oncology revealed low EPCAM expression in HCC, unlike its strong expression in other tumor types." (PMID 41228323, 2025).
tumor (continued). "By targeting multiple surface proteins, this approach captures CTCs that may not express EpCAM but do express HER2 or EGFR, thereby encompassing a broader range of tumor cell phenotypes." (PMID 40076201, 2025). "NP591 significantly reduced tumor growth in the RD, but not in the OVCAR-5 model, likely reflecting the potent antitumor activity of EpCAM CAR-T cells in this experiment, which could only be marginally enhanced by NP591." (PMID 38427724, 2024). "Importantly, their target antigens seem to be expressed by the epithelial tumor cells, highlighted by either EpCAM or CA125 epithelial cell markers, and not by the vimentin-expressing tumor stroma." (PMID 39086481, 2024). "Despite some inconsistency in the frequencies of detection of individual stemness and EMT features based on gene and protein expression in tumor cells, it can be assumed that EpCAMhigh CTCs are more likely to possess diverse stemness features and epithelial EMT phenotype than EpCAM-negative CTCs." (PMID 39456890, 2024). "Thus, EPCAMhigh tumor spots more often demonstrated the expression of such epithelial markers as KRT7, KRT8, and KRT18 compared to EPCAMlow and EPCAM-negative clusters." (PMID 39456890, 2024). "EpCAM+, but not CK+ DTCs in BM, predicted reduced PFS and tumor-specific survival." (PMID 37303738, 2023). "Additionally, to assess the contamination of tumour cells in metastatic samples, we examined the expression of oesophageal epithelium genes (KRT5, KRT19, EPCAM and SOX4) and found almost no cells that expressed these genes." (PMID 36650114, 2023). "However, it is deemed inappropriate for use in RCC due to the lack of epithelial cell adhesion molecule (EpCAM) and cytokeratin (CK) expression in CTCs that have undergone epithelial-mesenchymal transition (EMT), a very common phenomenon in this type of tumor." (PMID 37176111, 2023). "EpCAM+Vim+CD24+ cells were enriched in the stroma compared to the tumour body, and there was a much greater accumulation of EpCAM+Vim+CD24+ cells in the stroma of metastatic tumours compared to non-metastatic tumours." (PMID 37975646, 2023). "Notably, EpCAM BiTE induces CD4+ and CD8+ T-cell activation in the presence of EpCAM-positive tumor cells, like 4T1 and MC38-EpCAM, but not EpCAM-negative tumor cells, such as H22 and MC38." (PMID 36451817, 2022). "The results showed that not every tumor tissue expressed CD44, CD24 or ABCG2, but the expression of EpCAM could be detected." (PMID 36132125, 2022). "To investigate whether AB928 can shield CAR T cells from adenosine-mediated suppression, we cocultured anti-EpCAM CAR T cells and Panc02-EpCAM tumour cells in the presence or absence of inhibiting concentrations of NECA and serially titrated AB928." (PMID 36266575, 2022). "To expand the CD81 analysis in EpCAM+/− putative CTCs, we established a flow cytometry approach to gate single cells and clusters based on size channels (forward scatter and side scatter) as validated on clustering WT and non-clustering CD44KO tumor cells." (PMID 36193887, 2022). "In addition, after doxorubicin (DOX) treatment, the proportion of EpCAM+/CD133+ was significantly increased in the EpCAM−/CD133− nonstem HCC population, accompanied by more stemness properties and elevated tumor-forming ability." (PMID 36369033, 2022). "Interestingly, Cluster-6 shows expression for stemness markers CD117 and CD44, the tumor markers CD125, HE4 and EpCAM, and is negative for the immune and stromal markers, presenting as a potential cancer stem cell population." (PMID 33135052, 2021). "One reason for the stronger observations obtained for tumor-specific markers (CEA and HE4 mRNAs) may be the fact that EOC CTCs are heterogeneous and epithelial markers (i.e. EPCAM and MUC1 mRNAs) may not represent all parts of the tumor." (PMID 34006887, 2021).
tumor (continued). "Furthermore, it only selects CTCs expressing EpCAM; thus, other CTC phenotypes are missed, such as mesenchymal and stem cell-like tumour cells that have low levels or no EpCAM expression." (PMID 34503260, 2021). "However, combination with co-stimulatory αCD28 BiMAb recognizing HER2, EpCAM, EGFR or PD-L1 significantly enhanced the anti-tumor immune response compared to no-antibody controls as well as to single treatment with αHER2–αCD3." (PMID 34484225, 2021). "There is no doubt that the detection and analysis of CTC markers (EpCAM and CK8, 18, CD45 Vimentin, Twist and 19) and CSCs markers (Nanog) are useful for evaluating tumor progression, developing tumor drugs, and monitoring the disease process of cancer patients." (PMID 34123777, 2021). "IF staining using a pan-cytokeratin antibody, as well as seven additional epithelial proteins including CK5, CK18, CK19, EpCAM, E-Cadherin, P-Cadherin, and p63, confirmed that residual HER2/neu tumor cells generally lacked expression of epithelial markers, suggesting that they had undergone an EMT." (PMID 34088357, 2021). "EpCAM and CEA were not consistently expressed in tumor, stromal, or normal tissue." (PMID 32516897, 2020). "In GCT, the transmembrane epithelial adhesion molecule (EpCAM; CD326) constitutes a promising target for such an approach as it is broadly present on the surface of GCT of different origins irrespective of age, sex, site, and clinical tumor stage." (PMID 32438548, 2020). "Looking at the subgroup of EpCAM-positive serum exosomes, miR-200b was deregulated in non-metastasized UICC tumor stages II (2−ΔΔCq = 2.38, p = 0.02, r = 0.37) and III (2−ΔΔCq = 3.11, p = 0.013, r = 0.38) and when comparing all PDAC to healthy patients (2−ΔΔCq = 2.48, p = 0.008, r = 0.30)." (PMID 31941049, 2020). "Subsequent analysis found that EV EpCAM signal differed between healthy controls and PDAC patients with any histologic grade, tumor stage or degree of lymph node involvement, but was not significantly different among different levels of any of these tumor parameters." (PMID 31921310, 2019). "Although mechanisms have not been fully elucidated, the cell surface molecules, EpCAM and CD2433, have been shown to exert gelatinolytic activities that may contribute to tumor spreading." (PMID 29891938, 2018). "The aim of our study was to investigate EpCAM‐negative CTCs that were isolated from patients with metastatic breast cancer (mBC) and focus on LKB1 and ZEB1 expression to dissect their functional roles in triggering anoikis and tumor progression." (PMID 28700115, 2017). "The EpCAM+ CD44+ CD47+ MET+ phenotype is common and was found in the circulation of all patients at varying frequency, including the vast majority whose circulating tumor cells were not tumorigenic." (PMID 28721373, 2016). "In agreement with literature data, EpCAM should not to be used as the only CTC identification marker as it may underestimate the actual amount of circulating and/or disseminated tumor cells." (PMID 27527155, 2016). "Flow cytometric analyses of KUC4 and KUC11 DLBCL PDXs showed that tumor cells within the PDXs were predominantly positive for human CD45 and negative for human EpCAM, confirming that these tumors originated from human lymphocytes presented in the surgical specimens." (PMID 27367028, 2016). "Although pancreatic CSCs were described nearly ten years ago as CD44+/ CD24+/EpCAM+ cells or CD133+ cells, no study has determined the co-expression of all of these markers in PDAC either directly in the tumor samples or in the human PDAC cell lines derived from primary tumors." (PMID 27414409, 2016).
tumor (continued). "Median EpCAM+ taMPs values were significantly elevated (one-way ANOVA) in patients with CRC (n = 52), NSCLC (n = 40), PaCa (n = 11) by an average of 2.3 fold irrespective of the tumour entity and size." (PMID 27127176, 2016). "No expression of CTNNB1, CTLA4, EPCAM, ERBB2, MET, p40, PD-L1 and SOX2 could be detected in any of the tumors, PD-L1 was negative in tumor as well as stromal cells." (PMID 26943575, 2016). "Interestingly, we found that tumours from CD24- cells did not express the CD24 protein, and neither did they express the stemness markers CD47, EpCAM and Oct3/4." (PMID 25932953, 2015). "To investigate if PBLs transduced with the EpCAM-specific CAR can specifically target EpCAM+ cells, we compared the cell killing capabilities of PBLs on two different, luciferase-expressing tumor cell lines, PC3M with high expression of EpCAM and Hela cells that do not express EpCAM." (PMID 25636521, 2015). "More recently developed approaches have incorporated additional markers for CTC/DTC detection, including markers for the detection of tumor cells that have undergone EMT, and yielding improved sensitivity and the detection of EpCAM-negative subsets of CTC/DTCs." (PMID 25133137, 2014). "Further characterization identified the non-adherent cell population to be epithelial cell adhesion molecule (EpCAM) and CA125 positive EOC tumor cells, thus indicating that differential rates of adherence to plastic can be used to minimize contamination from other ascites cell types." (PMID 24860781, 2014). "Based on the absence of stromal staining, PSMA, EpCAM and VEGF show high tumor distinctiveness." (PMID 24727373, 2014). "Importantly, tumor fragments derived from CD133+/EpCAM+ tumor spheroid cells, but not from CD133−/EpCAM+ differentiated cells, demonstrated continual growth potential after re-implantation in the secondary mice." (PMID 23826249, 2013). "However, whether AKT or β-catenin may function as transcription factors of c-Myc and EpCAM regulated by SLC1A4 is still unclear, and the potential regulation of SLC1A4 in tumor microenvironment represented by cancer immunity is not referred to in this study." (PMID 39949345, 2025). "(F) Quantification of the percentage of EpCAM+Vim+CD24+, EpCAM+Vim+CD24- and pan-keratin+Vim+CD24+ cells in normal region (epithelium distant from the tumour), tumour body, and stromal region from metastatic and non-metastatic tumours in the first cohort of specimens." (PMID 37975646, 2023). "The IHC staining of co-cultures with GFP/luc-HT-29 revealed an effective tumor cell lysis and almost no remaining tumor cells in GLV-0b347-infected co-cultures compared to MOCK-treated co-cultures, as indicated by staining with hematoxylin and eosin (H&E) and EpCAM antibody." (PMID 36851574, 2023). "Starting with the EpCAM, Vimentin and CD24 immunofluorescence grey levels for each nucleated cell, we used a supervised machine learning approach to predict whether an imaging field comes from a metastatic or non-metastatic tumour." (PMID 37975646, 2023). "Thus, it should be considered that tumor-related inflammation and increased cell turnover could favor cancer-induced secretion of CD133+ and EPCAM+ EVs by non-malignant cells." (PMID 35267665, 2022). "Thus, the small number of eight subpopulations of EpCAM+CK7+ CTCs may be due not so much to a reduced capacity for intravasation, but to a small number of such cells in the primary tumor." (PMID 33801519, 2021). "The expression levels of mucin 1 (MUC1), epidermal growth factor receptor (EGFR), epithelial cell adhesion molecule (EpCAM), and extracellular matrix metalloprotease inducer (EMMPRIN) in tumor-derived MVs were used to distinguish cancer patients from healthy controls regardless of tumor type." (PMID 33499132, 2021). "Circulating tumor cells (CTCs) undergoing epithelial-mesenchymal transition (EMT) and CTCs reflecting a dedifferentiated CSC phenotype may not be detected using only an anti-EpCAM antibody to capture them." (PMID 32214335, 2020).